DUSP1 (dual specificity phosphatase 1)
Diseases named in the same sentence as DUSP1 in open-access papers (continued):
Sharing a sentence is not in itself a finding about the gene and the disease.
COVID-19 (6 papers, 2021 to 2024). A disease caused by infection with severe acute respiratory syndrome coronavirus 2. "The expression level of DUSP1 is particularly downregulated in the nasopharyngeal swabs and lung tissues of COVID-19 patients." (PMID 37853311, 2023). "Similarly, other genes involved in type I interferon signaling (IFITM1 and IFITM3) and cellular activation (UBC, FOS, and DUSP1) were increased in a severity-dependent manner, suggesting an enhanced EF B-cell activity associated with an overt inflammatory condition in severe COVID-19." (PMID 35899045, 2022). "It is possible that theophylline administration to COVID-19 patients increases the expression of DUSP1 and DUSP5 to such an extent that they contribute to the treatment of the illness." (PMID 35456985, 2022). "Here, the lower expression of DUSP1 observed in SARS-CoV-2 infected cells and nasopharyngeal swabs of severe COVID-19 patients was associated with the higher expression of TNF-α, IL-1β, and IL-1A genes (respectively)." (PMID 33995033, 2021). "Moreover, in COVID-19 patients, high levels of DUSP1 and DUSP5 have been detected, especially in severe cases." (PMID 35456985, 2022). "Among medications used for COVID-19, chloroquine increased both DUSP1 and DUSP5 expressions." (PMID 33995033, 2021). "Identifying elements contributing to the dysregulation of these pro-inflammatory cytokines during COVID-19, such as reduced expression of DUSP1 and DUSP5, may pave the way for therapeutic intervention to control the level of these cytokines and hence their pathological implications." (PMID 33995033, 2021). "•The expressions of other genes that are not included in the potential main pathway of steroids' anti-inflammatory effects, yet affected by steroid binding and its receptors, i.e., DUSP-1, JAK-1 and MAPK-1, were dramatically higher in mild COVID-19 patients." (PMID 38187222, 2024). "To confirm this observation, we analyzed the expression of DUSP1 and DUSP5 in nasopharyngeal swabs from severe COVID-19 patients recruited from a local hospital." (PMID 33995033, 2021). "Furthermore, our findings showed that other genes, including TSC22D3, DUSP-1, JAK-1, and MAPK-1 expressions, were significantly elevated in mild COVID-19." (PMID 38187222, 2024). "Given that the SARS-CoV-2 infection does increase the pro-inflammatory cytokines level, the combined effect of these medications on DUSP1 and DUSP5 expression might play a significant role in attenuating the immunopathology of COVID-19." (PMID 33995033, 2021). "Notably, the mitogen-activated protein kinase (MAPK) pathway (i.e., FOS, JUN, JUNB, and DUSP1) was greatly suppressed in all recovered patients compared with that in the HCs, which suggested that inhibition of the MAPK signaling pathway is a recovery sign of COVID-19 patient." (PMID 37853311, 2023).
Hepatic fibrosis (6 papers, 2017 to 2024). The presence of excessive fibrous connective tissue in the liver. "For instance, in the alcohol-induced OS state, low expression of dual-specificity phosphatase-1 (DUSP1) caused translocation of the E3 ubiquitin ligase component cullin-1 (CUL1) to the nucleus, leading to defective Parkin-mediated mitophagy and triggering hepatic fibrosis." (PMID 39183973, 2024). "Notably, DUSP1 transgenic (Dusp1Tg) mice showed resistance to alcohol-mediated hepatic dysfunction, as evidenced by decreased AST/ALT activity, improved alcohol metabolism, and suppressed liver fibrosis, inflammation, and oxidative stress." (PMID 37063418, 2023).
lung adenocarcinoma (6 papers, 2010 to 2024). A carcinoma that arises from the lung and is characterized by the presence of malignant glandular epithelial cells. "Compared with the stage II and stage IIIA samples, the stage I lung adenocarcinoma samples were marked by four differentially-expressed genes, DUSP1, Zimp7, EST NP_937824 and XM_498632." (PMID 24137407, 2013). "In the present study, DUSP1 mRNA was significantly downregulated in the lung adenocarcinoma tissues, and the levels declined progressively with the development of this cancer, which was consistent with the results reported with regard to epithelial carcinomas." (PMID 24137407, 2013). "We found that glucocorticoids rapidly increased transcription of DUSP1 within 10 minutes in A549 human lung adenocarcinoma cells." (PMID 21060794, 2010). "The analysis of DUSP1 expression may be useful to evaluate the disease extent and prognosis of lung adenocarcinoma." (PMID 24137407, 2013). "However, glucocorticoids are known to upregulate DUSP1/MKP-1 expression and not surprisingly dexamethasone effectively suppressed cisplatin-induced apoptosis in a lung adenocarcinoma cell line indicating that DUSP1/MKP-1 plays a key role in this potentially undesirable drug-drug interaction." (PMID 30401534, 2019).
myocardial infarction (6 papers, 2012 to 2024). Gross necrosis of the myocardium, as a result of interruption of the blood supply to the area, as in coronary thrombosis. "Jin et al44 indicated that dual specificity protein phosphatase 1 (DUSP1) can inhibit the activity of JNK, mitigating the binding of JNK and Mff promoter, thus decreasing the expression level of Mff after myocardial infarction and improving mitochondrial and cardiac function." (PMID 34160885, 2021).
sarcoidosis (6 papers, 2013 to 2024). Sarcoidosis is a multisystemic disorder of unknown cause characterized by the formation of immune granulomas in involved organs. "We have previously shown that DUSP1 expression is decreased in sarcoidosis AMs and monocytes and GCs induced DUSP1 expression at the protein level." (PMID 32477331, 2020). "This coincided with much lower DUSP1 protein expression in controls than sarcoidosis patients." (PMID 30764493, 2019). "Altered expression and activation of p38 and DUSP1 has also been observed in sarcoidosis." (PMID 30764493, 2019). "The top 50 overexpressed inflammatory genes in the ‘good treatment response’ sarcoidosis patients included anti-inflammatory genes e.g IL1R2, DUSP1, IL18R, C-FOS, IκBα and MAPK1." (PMID 23940611, 2013). "Previously, we have shown that sarcoidosis bronchoalveolar lavage (BAL) cells and alveolar macrophages (AMs), unlike those from healthy controls, exhibit high constitutively active p38 and lack dual specificity phosphatase (DUSP1 or MKP-1)." (PMID 30946009, 2019).
Cerebral ischemia (5 papers, 2020 to 2024). Restriction of arterial blood supply to the brain associated with insufficient oxygenation to support the metabolic requirements of the tissue. "Another study by Xu demonstrated that DUSP1 reduces ischemic reperfusion injury in the brain by inactivating the JNK-Mff pathway and inhibiting mitochondrial fission, thereby attenuating cerebral ischemia–reperfusion injury." (PMID 39697434, 2024).
cognitive decline (5 papers, 2016 to 2025). "In the human cortex, DUSP1 protein expression correlates with tau phosphorylation, synaptic defects and cognitive decline in subjects diagnosed with AD." (PMID 33603656, 2021). "In human cortex, DUSP1 protein expression correlates with tau phosphorylation, synaptic defects and cognitive decline in subjects diagnosed with AD." (PMID 27849045, 2016). "Additionally, RGS1 and DUSP1 are involved in inflammation and immune signaling, which are increasingly recognized as key contributors to cognitive decline." (PMID 40624693, 2025). "A second cohort with 29 subjects clinically diagnosed with AD and 17 non-demented controls all with cognitive assessments prior to death using the Mini-Mental State Exam (MMSE) permitted correlations of cortical expression of DUSP1 with an index of cognitive decline." (PMID 27849045, 2016).
endotoxemia (5 papers, 2013 to 2024). "Collectively, these findings substantiate the necessity of Dusp1 abundance in maintaining cardiomyocyte functionality and mitigating inflammatory responses in endotoxemia-induced cardiac dysfunction." (PMID 39659576, 2024). "In conclusion, our findings suggest that elevated Pgam1 expression in conjunction with dephosphorylated Dusp1 constitutes potential molecular underpinnings of myocardial dysfunction in endotoxemia, mainly through the perturbation of MQC." (PMID 39659576, 2024). "To demonstrate the cardioprotective role of Dusp1 against endotoxemia, we also generated the Dusp1 transgenic (Dusp1Tg) mice." (PMID 39659576, 2024). "This dephosphorylated state of Dusp1 significantly exacerbates cardiomyocyte dysfunction and disrupts MQC, marking a novel molecular pathway implicated in cardiac impairment during endotoxemia." (PMID 39659576, 2024). "A pivotal discovery of our study is the predominance of Dusp1 dephosphorylation as a molecular response to endotoxemia." (PMID 39659576, 2024). "To unravel the upstream mechanisms responsible for Dusp1 dephosphorylation during endotoxemia, we employed co-IP coupled with mass spectrometry (MS) analysis of Dusp1." (PMID 39659576, 2024). "Our findings substantiate the cardioprotective role of Dusp1 against myocardial injury induced by endotoxemia." (PMID 39659576, 2024). "First, Pgam1 and Dusp1 have emerged as potential biomarkers for myocardial dysfunction in endotoxemia, offering fresh perspectives on the biomolecular basis of this affliction." (PMID 39659576, 2024). "To elucidate the pathophysiological consequences of Dusp1 downregulation in endotoxemia-induced myocardial dysfunction, we engineered cardiomyocyte-specific Dusp1 knockout (Dusp1cko) mice and established a lipopolysaccharide (LPS)-induced endotoxemia myocardial model." (PMID 39659576, 2024). "Consequently, therapeutically targeting the Pgam1/Dusp1 axis emerges as a promising strategy to ameliorate cardiac function in endotoxemia-afflicted patients." (PMID 39659576, 2024). "Our research seeks to clarify the regulatory function of Pgam1 in Dusp1 dephosphorylation and subsequent degradation, potentially disrupting MQC in cardiomyocytes and exacerbating endotoxemia-induced myocardial injury." (PMID 39659576, 2024). "The interaction between increased Pgam1 and Dusp1 fosters dephosphorylation and subsequent degradation of Dusp1, exacerbating the impairment in MQC and contributing to myocardial dysfunction in endotoxemia." (PMID 39659576, 2024). "In addition, Dusp1 engages in an interaction with VCP, facilitating dephosphorylation and subsequently regulating mitochondrial fusion and fission as a defense mechanism against endotoxemia-triggered myocardial dysfunction." (PMID 39472573, 2024).
gallbladder cancer (5 papers, 2017 to 2024). "In gallbladder cancer, DUSP1 also inhibits cancer cell growth and metastasis via targeting the DUSP1-pERK-MMP2/VEGF signaling pathway." (PMID 29558404, 2018). "Furthermore, DUSP1 also made profound impacts upon proliferation in many types of cells, including keratinocytes, gallbladder cancer cells, high glucose-induced cardiac fibroblasts and small cell carcinoma of the prostate PC-3 cells." (PMID 34778900, 2022).
ischemia (5 papers, 2021 to 2025). A hypoperfusion of the BLOOD through an organ or tissue caused by a PATHOLOGIC CONSTRICTION or obstruction of its BLOOD VESSELS, or an absence of BLOOD CIRCULATION. "The overexpression of DUSP1 has a neuroprotective effect in response to ischemia and, together with DUSP4, they protect motor axons from degradation." (PMID 36227898, 2022). "Following ischemia/reperfusion, levels of dual-specificity protein phosphatase 1 (DUSP1) are significantly downregulated in coronary ECs, thus activating JNK, prior to translocation to the nucleus to promote Mff transcription." (PMID 34093852, 2021). "DUSP1, one of the central GSERK genes identified, encodes a dual-specificity phosphatase critically involved in attenuating excessive MAPK activation, thereby potentially limiting ischemia-induced neuroinflammation and neuronal cell death." (PMID 40636523, 2025). "The tissues of cerebral ischemic scars were taken for IHC staining and Western blotting, and the expressions of FOS, DDIT3, DUSP1 and NFIL3 after ischemia were detected." (PMID 38384585, 2024). "To evaluate the potential role of DUSP1 in IRI-induced AKI, we generated Dusp1 knockout mice and established AKI models with Dusp1 knockout (Dusp1−/−) and wild-type (WT) mice (bilateral ischemia for 28 min followed by reperfusion for 48 h)." (PMID 37935658, 2023).
leukemia (5 papers, 2021 to 2025). A malignant (clonal) hematologic disorder, involving hematopoietic stem cells and characterized by the presence of primitive or atypical myeloid or lymphoid cells in the bone marrow and the blood. "Another study showed that the enhanced MAPK signaling resulted in dependence on dual specificity phosphatase 1 (DUSP1) that augmented survival signaling, and further that combined use of a DUSP1 inhibitor in concert with trametinib eradicated leukemia." (PMID 41154433, 2025). "This includes genetic or pharmacological inhibition of DUSP1, which abrogates intrinsic resistance to TKIs in BCR-ABL1-induced leukemia." (PMID 36460969, 2022).
liver cancer (5 papers, 2017 to 2025). An epithelial or non-epithelial malignant neoplasm that arises from the liver. "DUSP1 is reportedly involved in the progression of some tumors, including prostate, colon and liver cancers." (PMID 28129656, 2017).
pulmonary fibrosis (5 papers, 2021 to 2025). Chronic progressive interstitial lung disorder characterized by the replacement of the lung tissue by connective tissue, leading to progressive dyspnea, respiratory failure, or right heart failure. "Bleomycin-induced lung injury is prevented in the DUSP1 proficient mouse model, whereas persistent lung fibrosis is observed in the DUSP1 deficient mice." (PMID 41158869, 2025). "Dysregulation of this balance is implicated in various diseases, including cancer and idiopathic pulmonary fibrosis, where overexpression of Dusp1 can lead to decreased Erk1/2 activity and hinder tumor cell and pulmonary fibroblasts proliferation." (PMID 39472573, 2024). "In another mouse model for lung fibrosis, DUSP1 was activated by the proteasome inhibitor bortezomib and reduced fibroblast proliferation." (PMID 34831059, 2021). "Moreover, a recent report suggests that DUSP1 is involved in pulmonary fibrosis by p32α inhibition and contributes to alterations in lung cellular phenotype in mouse models." (PMID 41158869, 2025). "Compared with CIH group, Dusp1 knockdown significantly enhanced the phosphorylation of Erk1/2 and Drp1, exacerbating remodeling, muscularization of distal pulmonary arteries, and pronounced pulmonary fibrosis around the pulmonary arterial tissues." (PMID 39472573, 2024). "It had been reported before that activation of DUSP1 in pulmonary fibrosis is anti-proliferative." (PMID 34831059, 2021). "Moreover, Cre recombinase–mediated deletion of Dusp1 in mouse fibroblasts initiated following peak bleomycin-induced pulmonary fibrosis abrogated spontaneous resolution in vivo, indicating that MKP1 served as a critical antifibrotic brake promoting fibrosis resolution." (PMID 38512415, 2024).
rheumatoid arthritis (5 papers, 2016 to 2024). A chronic, systemic autoimmune disorder characterized by inflammation in the synovial membranes and articular surfaces. "Notably, the increased expression in Dusp1 and Ptprs has been shown to occur due to many chronic inflammatory diseases, including cancer, rheumatoid arthritis, and ulcerative colitis." (PMID 38459711, 2024). "Among PSA T and NK cells, we also observed a downregulation of AP-1 transcription factors (JUN, JUNB, JUND, FOS) and regulators of activation (TNFAIP3, DUSP1) along with the upregulation of S100A11, a calcium-binding protein associated with rheumatoid arthritis." (PMID 35309349, 2022). "Some studies reported that DUSP1, DUSP2, and DUSP5 are involved in osteoclast-related diseases, such as osteoporosis and rheumatoid arthritis, but the role of DUSP6 has not been studied." (PMID 34475393, 2021).
allergic disease (4 papers, 2011 to 2026). An immune response that occurs following re-exposure to an innocuous antigen, and that requires the presence of existing antibodies against that antigen. "LOC101928093/DUSP1 has not been reported to be associated with any allergic disease previously." (PMID 34785669, 2021).
Arthritis (4 papers, 2015 to 2023). Inflammation of a joint. "Steroid injection is effective for arthritis, and dexamethasone is known to enhance DUSP-1 expression." (PMID 35008797, 2021). "DUSP-1 has been reported to play an important role in the development of arthritis." (PMID 35008797, 2021). "Previous studies indicate the importance of both ERK and p38 in the progression and initiation of arthritis as well as the role of DUSP1 in the negative regulation of these MAPKs." (PMID 26562438, 2015). "Although no reports to date have indicated that DUSP-1 may be useful for the treatment of LBP, some therapeutic agents for arthritis have been reported to induce DUSP-1." (PMID 35008797, 2021).
breast tumors (4 papers, 2017 to 2020). "Also, ATF4 downregulation was associated with decreased P21CIP1 and increased DUSP1 mRNA expression in the mouse breast tumor cells." (PMID 31086176, 2019). "In HER2+ breast tumors, DUSP1 displays anti-apoptotic effects by limiting the accumulation of phosphorylated active forms of JNK1/221." (PMID 31086176, 2019). "Further investigations are warranted to confirm the association of environmental factors, including fruit and soybean intake, irregular menstruation, and ER/PR status, with DUSP1 methylation in breast tumour DNA." (PMID 28220843, 2017). "Genomic DNA from 326 breast tumour tissue samples was detected for DUSP1 methylation: the positive frequency of DUSP1 methylation was 59.2% (193/326)." (PMID 28220843, 2017). "Second, our conclusion for the association between ER/PR status and DUSP1 methylation in breast tumour DNA was generated based on a population study without an experimental validation in vitro study." (PMID 28220843, 2017). "Phosphorylation of JNK1/2 downstream of ATF4 is mediated by the suppression of DUSP1, which plays an important role in the anti-tumor effects of PKR in mouse NEU breast tumors." (PMID 31086176, 2019). "Collectively, the data showed that ATF4 acts downstream of PKR and eIF2α-P in mouse NEU breast tumor cells to upregulate P21CIP1 and increase JNK1/2 phosphorylation via the downregulation of DUSP1." (PMID 31086176, 2019). "A critical novel finding of this study was the linkage of ER/PR-negativity with methylated DUSP1 in both breast tumour DNA and PBL DNA, which might account for the lower MKP-1 expression." (PMID 28220843, 2017).
coronary artery disease (4 papers, 2018 to 2023). "Moreover, the increase in DUSP-1 expression associates with increased EZH2 expression in coronary artery disease (r2 = 0.4541, p = 0.0030) and the increase in DUSP-1 expression tends to associate with decreased MAPK7 expression (r2 = 0.1686, p = 0.1016), although not significantly." (PMID 34493753, 2021). "Another study also identified a series of immune cell-related genes, including FOS, DUSP1, CXCL8, and NFKBIA, which can not only differentiate between AMI and coronary heart disease (CHD) but also predict the risk of HF in AMI patients." (PMID 37965091, 2023). "Nonetheless, the expression of DUSP-1 is associated with an increasing IMT, and a decreased expression of MAPK7 in coronary artery disease." (PMID 34493753, 2021). "In human coronary artery disease, DUSP-1 expression is increased in advanced lesions (IMT > 3, p < 0.001) and increasing IMT associates with increased DUSP-1 expression (r2 = 0.2767, p = 0.0301)." (PMID 34493753, 2021). "Moreover, it has been reported that expression levels of DUSP1 in circulating blood cells exhibited a more consistent difference between patients and controls in identifying coronary artery disease history when compared with hsCRP." (PMID 30647800, 2018).